SIRT1 (sirtuin 1)
Diseases named in the same sentence as SIRT1 in open-access papers (continued):
Sharing a sentence is not in itself a finding about the gene and the disease.
myocardial infarction (continued). "In a myocardial infarction study, the activation of the SIRT1/AMPK signaling pathway following traditional Chinese medicine intervention promoted mitophagy, which in turn suppressed oxidative stress and inflammatory responses in cardiomyocytes, thus improving cardiac function." (PMID 40761388, 2025). "SIRT1 enzyme has been investigated because of its potential to develop new therapeutic tools for the prevention/treatment of several age-related chronic diseases, including myocardial infarction." (PMID 41302436, 2025). "Furthermore, lncRNA KLF3‐AS1 suppresses miR‐138‐5p to increase SIRT1 expression, thereby attenuating cardiomyocyte apoptosis during myocardial infarction." (PMID 41445977, 2025). "In mice with myocardial infarction, curcumin can reduce the expression of human silencing regulatory protein 1 (SIRT1) after myocardial infarction, suggesting that SIRT1 activation may be the target of curcumin-mediated myocardial protection." (PMID 38444481, 2024). "Furthermore, in models of myocardial infarction/reperfusion injury, curcumin effectively decreased oxidative stress-induced damage to mitochondria reduced infarction size through a SIRT1 pathway." (PMID 37630770, 2023). "KLF3-AS1 in exosomes secreted from MSC can regulate Sirt1 so as to attenuate myocardial infarction." (PMID 36627572, 2023). "Moreover, an experiment in an animal model of acute myocardial infarction has shown that miR-124-3p targets SIRT1 to influence cell apoptosis, inflammatory responses, and oxidative stress through regulation of the FGF21/CREB/PGC1α axis." (PMID 37441551, 2023). "Additionally, SUV39H1 inhibition has been found to protect mice from myocardial infarction by preventing SIRT1 transcriptional repression." (PMID 37758732, 2023). "The SIRT1 enzyme has been widely described as a challenging target for multiple strategies addressed for the prevention/treatment of several chronic age-related diseases, including myocardial infarct." (PMID 36235072, 2022). "Additionally, mangiferin increased FOXO3a deacetylation by upregulating SIRT1 in myocardial infarction, thereby preventing apoptosis and significantly reducing the size of myocardial infarction." (PMID 35855865, 2022). "EVs have attracted the attention of many scientists as a good carrier for treating the diseases, such as Qing Mao has researched that lncRNA KLF3-AS1 in human mesenchymal stem cell-derived EVs ameliorates pyroptosis of cardiomyocytes and myocardial infarction through miR-138-5p/Sirt1 axis." (PMID 34976968, 2021). "AntimiR199a therapy up-regulates Sirt1 and inactivates the co-activator P300 protein, thus leading to Yy1 inhibition which decreases both expression and release of circulating sST2 by cardiomyocytes after myocardial infarction." (PMID 33594087, 2021). "Moreover, Sirt1 protects cardiac function, reduces cardiac remodeling, inhibits cardiomyocyte apoptosis, and attenuates cardiomyocyte hypertrophy post-myocardial infarction." (PMID 31881009, 2019). "Having established that SUV39H promotes ROS generation and SIRT1 trans-repression in the process of myocardial infarction, we asked whether the ability of SUV39H to regulate ROS levels in cardiomyocytes depends on SIRT1." (PMID 28361889, 2017). "For example, the white wine component, n-tyrosol pretreatment could confer cardioprotection against an ischemic insult in rat model of myocardial infarction through the activation of AKT/FOXO3/SIRT1 pathway." (PMID 28112228, 2017). "Therefore, SUV39H links SIRT1 trans-repression to myocardial infarction providing rationale for targeting SUV39H1 in the development novel therapeutic strategies to treat ischaemic heart disease." (PMID 28361889, 2017). "Moreover, inhibition of eNOS activity blunted the beneficial effects of SIRT1 on myocardial infarct size." (PMID 26489513, 2015).
myocardial infarction (continued). "Using inhibitors of ATM, such as KU60019, ultimately restored levels of LARP7, SIRT1 and mitochondrial biogenesis preventing adverse remodeling effects of myocardial infarction (MI)." (PMID 40264508, 2025). "SIRT1 may be a new promising therapeutic target for myocardial infarction." (PMID 33879068, 2021). "Consistently, following acute myocardial infarction (AMI), we observed a marked decrease in Sirt1 expression, accompanied by an increase in Hif-1α and the cleaved caspase-3/caspase-3 ratio within the infarcted myocardial regions." (PMID 40087582, 2025). "Despite these insights, the precise relationship between Sirt1 and AMI, particularly in the milieu of cardiomyocytes post-myocardial infarction (MI), remains inadequately elucidated." (PMID 40087582, 2025). "Additional investigations have elucidated that RSV restores mitochondrial quality control following MI/R injury by activating SIRT1/SIRT3-mediated autophagy pathways and reverses cardiac remodeling following extensive myocardial infarction." (PMID 37754811, 2023). "For example, the activation of the AMPK/SIRT1/FOXO1 and SIRT1/AMPK signaling pathways promotes autophagy, reduces oxidative stress in myocardial cells, significantly reduces myocardial infarct size, and improves heart function." (PMID 37754811, 2023). "In conclusion, NXT can enhance ATP synthesis, regulate energy metabolism and mitochondrial biosynthesis by enhancing the expression of SIRT1, PGC-1α, and ATP5D during myocardial infarction and further exert its protective effect on ischemic myocardial tissue." (PMID 35915610, 2022). "Expressions of SIRT1, PGC-1α, and ATP5D proteins related to energy metabolism were decreased after myocardial infarction." (PMID 35915610, 2022). "We did not observe any difference between the groups in relation to myocardial infarction area, total and phosphorylated NF-kB, total and acetylated FOXO1, SIRT1 and Nrf-2 protein expression." (PMID 31751439, 2020). "This study showed Wenxin Keli regulates AMPK, SIRT1, and PGC-1α in myocardial infarction-induced heart failure rats, restoring mitochondrial oxidative phosphorylation by dual modulation of fatty acid/glucose pathways, distinct from trimetazidine, which primarily suppresses fatty acid metabolism." (PMID 40994651, 2025). "Recent studies have identified SIRT1 as a key modulator of autophagy, including its role in alleviating mitochondrial damage via the PINK1‐Parkin autophagy pathway, thereby protecting against post‐myocardial infarction remodelling in heart failure models." (PMID 40026072, 2025). "Particularly, transcriptional program for a mesenchymal MMP-dependent motility (i.e., EMT) is triggered in myocardial cells through Snail1 lactylation following myocardial infarction as well as in thyroid and renal carcinomas through LDHA- or Sirtuin 1-dependent mechanisms." (PMID 40434517, 2025). "miR-34a plays pro-apoptotic and pro-senescence roles in mesenchymal stem cell by targeting SIRT1; furthermore, inhibition of miR-34a might have important therapeutic implications in MSC-based therapy for myocardial infarction." (PMID 35265142, 2022). "We detected a negative correlation between recurrent myocardial infarction and left ventricular ejection fraction, (r=−0.233; p=0.033) as well as between SIRT1 values and left ventricular ejection fraction (r=−0.162; p=0.029)." (PMID 31143479, 2019). "Although their sample size is too small to create a generalizable classification based on CCC9 or SIRT1 reactivity, their study demonstrates a promising technique to differentiate CBN due to myocardial infarction (i.e., CCC9+/SIRT1−) from other etiologies of contraction bands." (PMID 28386585, 2017). "Sirt1+/− showed a comparable infarct size with aged hearts, while wild-type littermates had no apparent discrepancy in myocardial infarction compared to young hearts." (PMID 24040162, 2013).
myocardial infarction (continued). "Resveratrol, a polyphenolic activator of SIRT1, has been shown to increase the expression of eNOS and the combination of resveratrol with the HMG-CoA reductase inhibitors (statins) increased the activation of eNOS resulting in increased functional recovery in a model of acute myocardial infarction." (PMID 23284668, 2012).
Hypertension (106 papers, 2011 to 2026). The presence of chronic increased pressure in the systemic arterial system. "By activating endothelial nitric oxide synthase (eNOS), SIRT1 boosts nitric oxide (NO) production, which supports vasodilation, regulates blood flow, and reduces the risk of hypertension." (PMID 40565222, 2025). "Maternal-high-fat-diet-primed hypertension is associated with the inhibitory AMPK/SIRT1/PGC-1α pathway in an offspring’s kidneys." (PMID 37375602, 2023). "Increasing SIRT1 expression in mice improved vascular remodeling and hypertension caused by angiotensin II." (PMID 34730891, 2021). "It has been shown that SIRT1 level is reduced in Klotho deficient rats and activation of SIRT1 attenuates Klotho deficiency-induced arterial stiffness and hypertension." (PMID 34670596, 2021). "A recent study in rats with Klotho haplo-deficiency showed that this genetic defect is associated with arterial stiffening and hypertension and with decreased expression of SIRT1; and activating the SIRT1 gene abolished these defects." (PMID 34670596, 2021). "A recent study on Klotho haplodeficient mice showed that Klotho deficiency led to arteriosclerosis and hypertension, but these effects were diminished by increasing SIRT1 activity." (PMID 34730891, 2021). "Our previous study reported that resveratrol, a known natural activator of AMPK, prevents hypertension programmed by HFD associated with increased protein levels of SIRT1 and AMPKα2." (PMID 32053935, 2020). "Hypertension programmed by a maternal methyl-donor diet is associated with the reduced expression of nutrient-sensing signaling in several forms, including Sirt1, Pparb, Pparg, and Prkaa2." (PMID 32545526, 2020). "In this work, we observed, for the first time, that that maternal melatonin therapy prevents hypertension associated with increased expression of Sirt1, Sirt4, Prkaa2, Prkab2, Pparg, and Ppargc1a in adult offspring kidneys." (PMID 29641494, 2018). "The present animal studies reveal that endothelial overexpression of SIRT1 prevents adverse vascular remodeling and hypertension in eNOS-deficient mice." (PMID 27259994, 2016). "In this context, the overexpression of SIRT1 has been reported to attenuate angiotensin II-induced vascular remodelling and hypertension, which might be caused by SIRT1-induced downregulation of the angiotensin II type 1 receptor (AGTR1)." (PMID 37175937, 2023). "Likewise, melatonin’s protection of adult offspring against hypertension is associated with the activation of the AMPK/SIRT1/PGC-1α pathway." (PMID 35624788, 2022). "Based on the fact that SIRT1/FOXO3a signaling also plays a major role in autophagy regulation, we investigated whether this pathway is associated with renal fibrosis and hypertension-induced autophagic stress both in vivo and in vitro." (PMID 35222012, 2021). "Activation of SIRT1 attenuates Klotho Deficiency-induced hypertension and arterial stiffness." (PMID 32509148, 2020). "Moreover, SIRT1 gene was also reported significantly associated with ambulatory blood pressure level in patients with hypertension." (PMID 33324265, 2020). "Statistical results of sirtuin 1 (SIRT1) with hypertension (HT), coronaryartery disease (CAD), and peripheral artery disease (PAD)." (PMID 41259217, 2026). "In aortas of Ang II-induced hypertensive mice, the activity of SIRT1 was reduced since overexpression of SIRT1 or its activation by resveratrol reversed hypertension and vascular remodeling by reducing the binding of NF-κB on the promoter of TGF-β1." (PMID 41011644, 2025). "This investigation assessed empagliflozin’s therapeutic effects on hypertension, proteinuria, and kidney injury, with specific emphasis on SIRT1 activation." (PMID 40989847, 2025). "SIRT1 plays a pivotal role in the regulation of oxidative stress in hypertension and DN by regulating ACE2 expression." (PMID 38835661, 2024).
Hypertension (continued). "Researchers have found that the overexpression of SIRT1 can protect mice from vascular remodeling and hypertension induced by angiotensin II (Ang II)." (PMID 39234603, 2024). "In the hypertensive paraventricular nucleus (PVN) of the hypothalamus, inhibition of SIRT1 has been shown to promote inflammasome activation, aggravating hypertension." (PMID 39592923, 2024). "In conclusion, SIRT1 has a significant protective effect on a variety of endocrine diseases, such as hyperuricemia, hypertension, polycystic ovarian syndrome, osteoporosis, by regulating a variety of target genes." (PMID 36632457, 2023). "Another study explored perinatal melatonin therapy and found that its beneficial actions against high-fructose plus high-salt diet-induced offspring hypertension were related to regulating renal AMPKα2, AMPKβ2, SIRT1, SIRT4, PPARγ, and PGC-1α expression." (PMID 37175813, 2023). "These observational studies also found an association between telomere attrition and other parameters such as adiposity, hypertension or circulating sirtuin-1 concentrations." (PMID 37854186, 2023). "It has been found that SIRT1 inhibition in SIRT1+/− mice induces typical manifestations of PE, such as arterial hypertension, proteinuria, intra-uterine growth retardation, renal damage, as well as labyrinthine layer atrophy." (PMID 38003402, 2023). "As a reprogramming strategy, resveratrol has been utilized to avert maternal-high-fat-diet-primed hypertension in offspring by restoration of the SIRT1/AMPK/PGC1-α pathway." (PMID 37375602, 2023). "In a maternal methyl-donor diet model, offspring hypertension coincided with the reduced renal expression of SIRT1, AMPKα2, PPARβ, and PPARγ." (PMID 37175813, 2023). "Increased BP during hypertension-induced changes in the expression levels of longevity proteins such as SIRT1 is due to mitochondrial dysfunction." (PMID 35897743, 2022). "Previous studies have demonstrated that Sirt1 can play a protective role against experimental hypertension." (PMID 35561022, 2022). "High expressions of IGF-II were observed in the hearts of the hypertension model with widely dispersed apoptosis through JNK-activated SIRT1 degradation." (PMID 36005430, 2022). "Our results provided clear in vivo experimental support that a bioactive dipeptide combined with exercise protects the myocardium from hypertension by alleviating fibrosis, hypertrophy, and inflammation through AMPKα1/SIRT1/PGC1α." (PMID 35897743, 2022). "A maternal methyl-donor diet led to offspring hypertension accompanied by reduced renal expression of several nutrient-sensing signaling components, comprising AMPKα2, SIRT1, PPARβ, and PPARγ." (PMID 35624788, 2022). "DIKTNKPVIF potato peptides prevent hypertension by upregulating the mitochondrial biogenesis (AMPKα/SIRT1/PGC1α/p-Foxo3a/Nrf2/CREB) pathway." (PMID 35897743, 2022). "Typical pre-eclampsia-like symptoms, such as hypertension, proteinuria, fetal growth restriction, kidney injury, and a narrow placental labyrinth layer, were observed in SIRT1 knockdown (SIRT1+/−) mice." (PMID 35327614, 2022). "In our present study, IF treatment, along with swimming exercise, prevents hypertension in rats through synergistically modulating AMPKα1, SIRT1, and PGC1α signaling." (PMID 35897743, 2022). "Soy peptide VH-4, along with exercise, acts synergistically and prevents hypertension by activating cell survival and AMPKα1, Sirt1, PGC1α, and FoX3α proteins." (PMID 36431802, 2022). "Another study showed that the use of melatonin in gestation and lactation prevented hypertension programmed by a combined high-fructose plus post-weaning high-salt diet via regulating SIRT1, SIRT4, AMPKα2, AMPKβ2, PPARγ, and PGC-1α in the kidneys." (PMID 35624788, 2022). "We believed that the inability to reduce knockdown-SIRT1-induced hypertension via intragastric administration was related to the drug dosage." (PMID 35327614, 2022).
Hypertension (continued). "ARB prevents hypertension-enhanced cardiac apoptosis via enhancing SIRT1 longevity signaling and enhances the mitochondrial biogenetic survival pathway." (PMID 36005430, 2022). "Our results showed that administration of resveratrol in the PVN decreased ROS expression, restored neurotransmitter balance, and subsequently attenuated high blood pressure in 2K1C rats via the SIRT1/NF-κB pathway." (PMID 36235829, 2022). "SIRT1 and Klotho levels increase in pre-hypertensive patients before they decrease with the onset of hypertension and progression of the disease." (PMID 34670596, 2021). "SIRT1 level was significantly reduced in the ischemic (left) kidney in acute and chronic phases of hypertension." (PMID 34730891, 2021). "As angiotensin II and SIRT1 counteract each other's expression, a SIRT1 reduction in the heart and kidney, along with the influence of systemic/local angiotensin II, seems to be partly responsible for hypertension development." (PMID 34730891, 2021). "Changes in the function of SIRT1 and SIRT3 significantly affect the vascular function associated with hypertension." (PMID 34331512, 2021). "In hypertension-induced renal injury, urinary SIRT1 expression was decreased by miR-34a, indicating that SIRT1 is a potential method to evaluate renal injury in hypertensive patients." (PMID 35155600, 2021). "In contrast, the cerebral cortex Bcl-2 family-related and Sirt1/PI3K/AKT related pro-survival pathways were suppressed by early aged hypertension and were enhanced after EGCG treatment." (PMID 34456710, 2021). "Previous study showed that resveratrol increased the levels of sirtuin-1 (SIRT1) and PPARα to mediate its protective effect on hypertension under maternal HFD in the kidneys of male progeny." (PMID 33519432, 2020). "In light of the proven crosstalk between SIRT1 and AMPKα activity, SIRT1 activation can be a potential medical target to improve arterial stiffness and hypertension due to Klotho repression." (PMID 33117155, 2020). "In vivo, overexpression of NAMPT protected against angiotensin II- (Ang II-) induced hypertension by inhibiting ROS production via sirtuin 1 in mouse aortic endothelial cells (MAECs) and mouse aortic vascular smooth muscle cells (MOVAs)." (PMID 33488923, 2020). "Subcutaneous infusion of Ang II caused more serious hypertension, vascular remodeling, oxidative stress, NLRP3 inflammasome activation, AMPK phosphorylation inhibition, and SIRT1 downregulation in the aorta of FNDC5−/− mice than those of WT mice." (PMID 32509148, 2020). "Expression levels in spontaneously hypertensive rats have been reported to be higher than those in normal rats, and the occurrence of hypertensive left ventricular hypertrophy has been positively correlated with SIRT1 mRNA levels in myocardial tissue." (PMID 32757458, 2020). "The RSV/QSC treatment increased SIRT1 and SIRT3 expression independently from their role in the regulation of some the mechanisms that underlie hypertension studied in this paper." (PMID 32210194, 2020). "Another important result is that overexpression of Sirt1 exerts beneficial effects contrasting the angiotensin II-induced vascular remodeling and attenuating hypertension in mice." (PMID 33238655, 2020). "Collectively, this study is the first to show that NAMPT prevents Ang II-induced hypertension by inhibiting excess ROS accumulation, at least in part through the regulation of SIRT1 expression and the NAD concentration." (PMID 33488923, 2020). "Another study demonstrated that maternal melatonin therapy prevented a hypertension programmed high-fructose/high-salt diet by regulating Sirt1, Sirt4, Prkaa2, Prkab2, Pparg, and Ppargc1a." (PMID 31766163, 2019). "This is consistent with our previous report showing that activation of the AMPK/SIRT1/PGC-1α pathway related to the reprogramming effects in another model of programmed hypertension." (PMID 31416234, 2019).